IL6 (interleukin 6)
Diseases named in the same sentence as IL6 in open-access papers (continued):
Sharing a sentence is not in itself a finding about the gene and the disease.
cancer (continued). "Interleukin (IL)-6 plays key roles in the development of liver fibrosis and cancers." (PMID 27434097, 2016). "Furthermore, a strong correlation between the IFN-γ/IL-6 cytokine ratio and the therapeutic efficacy of cancer treatments has been reported." (PMID 27821803, 2016). "Previous studies have shown that the IL-6 induces the expression of miRNA-21 in cancer cells." (PMID 26837852, 2016). "Although, polyphenols from blueberry have demonstrated inhibitory activities on cancer cells via the control of inflammatory cytokines such as IL-6, dramatic and biphasic increase of IL-6 occurs early in CSC cellular transformation, independently of STAT3 decrease." (PMID 26762586, 2016). "IL-6 seemed to be a key mediator of muscle wasting in cancer cachexia." (PMID 26985904, 2016). "IL-6 is known to promote cancer cell proliferation and survival." (PMID 27487154, 2016). "Although the mechanisms underlying malignant cells in manipulating the macro environment and the metabolic pathway in cancer hosts, several inflammatory cytokines, including interleukin-6 and tumor necrosis factor-α, have been shown, in preclinical tumor models, to induce cancer cachexia." (PMID 26879126, 2016). "gp130 antagonists could be a new effective class of drugs which target IL-6 signaling to treat cancer." (PMID 26840088, 2016). "IL-6 is a cytokine that has been extensively studied in cancer research." (PMID 27174914, 2016). "The hallmarks of cancer-related inflammation comprise many key inflammatory factors, such as IL-6." (PMID 27557497, 2016). "Selective inhibition of COX-2 activity with celecoxib in senescent fibroblasts significantly constrained the release of PGE2 and SASP component IL-6, and diminished chemotaxis of cancer cells in vitro to levels similar to those of untreated proliferating control." (PMID 27385366, 2016). "In contrast, the luminal miRNAs targeted transcription factors that controlled EMT (ZEB1/2), and biomarkers associated with fibrosis and actin cytoskeleton (collagens), and basal cancer biology (IL6, EGFR, STAT3), all of which are suppressed in luminal cancers." (PMID 27845906, 2016). "Measurement of IL‐1β, IL‐6, and TNFα serum levels may help identify early cancer progression among patients with CRP <5 mg/L in routine practice." (PMID 26799163, 2016). "It should be noted that, in contrast to STAT1/2/5 proteins, constitutive and IL-6-induced STAT3 phosphorylation was shown to be reduced upon treatment by SFN in a number of cancer cell lines, thus revealing multiple modes of regulation of STAT proteins by ITCs." (PMID 27304884, 2016). "Targeted inhibition of IL-6 signaling is clinically used for treatment of rheumatoid arthritis and other autoinflammatory diseases (Tocilizumab), and has shown promising results in preclinical studies and clinical trials in various cancers." (PMID 27916836, 2016). "In addition, an immunohistochemical examination showed that the cancer cells were positive for IL-6." (PMID 27659803, 2016). "The data reported here support the notion that IL-6 could contribute to the aggressive features of these tumors and particularly the cancer stem like compartment." (PMID 27732936, 2016). "hepatocyte growth factor (HGF), interleukin-6 (IL-6) and other cytokines/chemokines derived from mesenchymal cells may promote de-differentiation, although their roles in triggering cancer cell EMT are not fully understood yet." (PMID 26985909, 2016). "Our study also highlights the question of whether other inflammatory cytokines, for instance, TNF or IL-6 (both also induced by ingenol mebutate), are also involved in the anti-cancer efficacy of ingenol mebutate." (PMID 27100888, 2016). "The data presented in this paper strongly support the idea that IL-6 inhibitors may be of great benefit to cancer patients." (PMID 27531896, 2016). "IL-6 is one of the most widely investigated cytokines in various diseases including cancer." (PMID 27034885, 2016).
cancer (continued). "It is reported that IL-6 also plays an important role in other cancer." (PMID 25785838, 2015). "Interestingly, on the promoters of factors like IL6 and ADORA1, which are upregulated in cancers and are associated with poor prognosis, histone acetylation was found to be significantly repressed upon luteolin treatment." (PMID 26517526, 2015). "Caspases are cytoplasmic, aspartate-specific cysteine proteases whose activation is required for apoptosis, and increased expression of anti-apoptotic factors by the IL-6/STAT3 signaling pathway may reduce caspase-mediated apoptosis in cancer cells." (PMID 25789077, 2015). "Plasma IL-6 should be further explored as frailty biomarker in cancer patients." (PMID 25989735, 2015). "However, a more specific study of the adequacy of the IL6/IL-10 ratio in the setting of cancer cachexia is necessary." (PMID 26508818, 2015). "Furthermore, since the PGE2-TNFα-IL-6 pathway is considered to likely occur in other cancer, the interference of such positive regulation is a reasonable target for anti-cancer strategies." (PMID 25785838, 2015). "IL-6 is a glycoprotein and a multifunctional cytokine that, in addition to its more well-known roles as a pro-inflammatory and sclerotic agent, affects the activity of cancer cells." (PMID 26418748, 2015). "Moreover, a number of studies have demonstrated that cancer-prone cytokines, such as interleukin 6 and vascular endothelial growth factor, are produced significantly more after open than laparoscopic surgery." (PMID 25887554, 2015). "Cancer patients that show improvement in fatigue show decreases in IL-6." (PMID 26469939, 2015). "The markedly reduced production of proinflammatory mediators, such as CCL2, interleukin-6 (IL-6), and the proangiogenic VEGF, may underlie the strong association between chronic inflammation and cancer progression." (PMID 26089739, 2015). "Important cytokines and mediators involved in the induction and perpetuation of the inflammatory environment in cancer, such as IL-6, IL-1β, macrophage colony-stimulating factor (M-CSF) and cyclooxygenase 2 (Cox2), have the transcription factor STAT3 as a crucial regulator of their expression." (PMID 26501341, 2015). "Further studies to elucidate the specific role of IL-6 in cancer pathogenesis are required." (PMID 26096712, 2015). "In a sample of cancer patients prior to surgery, fatigue correlated with levels of IL-6; another study reported that fatigue that follows cancer treatment correlated with levels of IL-6." (PMID 26469939, 2015). "Moreover, JAK2-specific inhibition blocks STAT3 phosphorylation and IL-6 production in cancer cells." (PMID 26491227, 2015). "Monocytes, known as the key component of inflammation system, might directly stimulate cancer cell growth by producing various proinflammatory cytokines, such as interleukin-1, interleukin-6, and tumor necrosis factor." (PMID 25994571, 2015). "In this study, we found that PCT and IL-6 could have a role in predicting cancer as our findings showed that PCT and IL-6 levels were higher in cancer patients than normal subjects." (PMID 26148092, 2015). "We hypothesised that therapy-induced stromal IL6 secretion would stimulate STAT3 in neighbouring cancer cells." (PMID 25915429, 2015). "Likewise, other studies using anti-IL-6 antibodies, either in vitro or in vivo, showed improvements in cancer cachexia." (PMID 26508818, 2015). "IL-6 was also a direct target of let-7 to inhibit cancer cell invasion and migration." (PMID 26123544, 2015). "The serum levels of pleiotropic cytokine IL-6 are increased in malignant tumors." (PMID 26538839, 2015). "We further investigated cancer cellular response to IL-6 treatment." (PMID 26258407, 2015). "What’s more, such confounding is difficult to exclude completely; however it is unlikely that it would explain our finding that IL-6 gene -174CC genotype was associated with lowered circulating IL-6 without predicting a low cancer risk." (PMID 26096712, 2015).
cancer (continued). "In addition, MSC-secreted IL-6 increases cancer cell secretion of endothelin-1 (ET-1), which then stimulates endothelial cells to form new blood vessels." (PMID 26517517, 2015). "As recently suggested, IL-6/STAT3 signaling also promotes stem cell-like phenotype of cancer cells." (PMID 26046794, 2015). "However, inflammatory models of chronic disease and clinical observations identify IL-6 activity as detrimental in autoimmunity and cancer." (PMID 26501341, 2015). "In addition to SDF1, interleukin-6 (IL-6) is also an important secreted soluble factor that plays crucial role in the crosstalk between cancer cells and their microenvironment." (PMID 26338965, 2015). "Among these, interleukin-6 (IL-6) takes a center stage in human cancer development and metastasis." (PMID 26258407, 2015). "IL-6 is a major inflammatory mediator and its uncontrolled production leads to chronic inflammation such as RA, inflammatory bowel disease, multiple sclerosis, and also many types of cancer." (PMID 26501341, 2015). "We can hypothesize that some cytokine from cancer cells promotes the transition of resident fibroblasts into CAFs, and this change leads to IL-6 secretion." (PMID 26690480, 2015). "In the present study, NF-κB, as a key inflammatory transcriptional factor, was found to be inactivated in hUC-MSCs stimulated with IL-6; this provides a possible explanation for the fact that several cancer-promoting cytokines were suppressed in the supernatant from hUC-MSCs pre-treated with IL-6." (PMID 25483835, 2015). "IL6, has been reported to induce cell proliferation in various cancers." (PMID 26053043, 2015). "Furthermore, activation of the intracellular Janus kinase (JAK)/STAT3 signaling pathway by IL-6 results in the expression of various genes involved in cancer growth and development." (PMID 25789077, 2015). "Importantly, the inhibition of ATM abrogated IL-6's effect on cancer nests formation in the lung of NCI-H446 or A549 cells transferred recipients." (PMID 26528698, 2015). "Interleukin-6 (IL-6), a pleiotropic cytokine with a variety of biological activities, is secreted by different cell types including macrophages, T- and B-lymphocytes, fibroblast, endothelial cells, keratinocytes and cancer cells." (PMID 25761055, 2015). "Interestingly, earlier studies have shown that PPIs inhibit the expression of proliferation markers in cancer cells through regulation of IL-6/STAT3 pathway." (PMID 26231702, 2015). "Whether IL-6 in an inflammatory microenvironment acts on MSCs and induces them to acquire the cancer-promoting phenotype remains unknown." (PMID 25483835, 2015). "The possible explanation may be that NF-κB is a well-known downstream of Akt in cancer, and NF-κB can directly bind to IL-6 promoter and subsequently activate IL-6 gene expression." (PMID 25504436, 2015). "Both IL-8 and IL-6 are involved in IR inflammatory response, enhancing cancer cell invasiveness." (PMID 25705130, 2015). "Interleukin-6 (IL-6), a multifunctional cytokine, plays a central role in regulating inflammatory and immune responses, and important roles in the progression, including proliferation, migration, and angiogenesis, of several cancers." (PMID 26690480, 2015). "Serum IL-6 levels may predict survival in cancer patients, including both lung cancer and HNSCC patients." (PMID 26079381, 2015). "Indeed, amongst SASP-secreted cytokines there is IL6, which is also present in the media of fibroblasts and cancer cells in co-culture." (PMID 25915429, 2015). "We then evaluated the effects of IL-6 on the growth abilities of cancer cells." (PMID 25797257, 2015). "Furthermore, IL-6 acts as an essential factor mediating the interaction between MSCs and cancer cells." (PMID 25483835, 2015). "Increased cancer cell invasion was reduced upon the inhibition of IL-6, MMP-3 and u-PA." (PMID 26284488, 2015). "Also IL-6 has growth factor properties, suggesting its role in the development and progression of cancer." (PMID 26535093, 2015).
cancer (continued). "Signal transducers and activators of transcription 3 (STAT3) is the main transcription factor through which IL-6 signals in target cells, where it regulates many genes including those that promote cancer proliferation and metastasis (e.g., TGF-β1) and angiogenesis (e.g., HIF-1α)." (PMID 26016502, 2015). "Moreover, IL-6 is emerging as a crucial mediator and a novel therapeutic target for chronic inflammatory diseases and cancer." (PMID 25884025, 2015). "Specifically, neutrophils contain multiple enzymes such as, myeloperoxidase, interleukin-6 (IL-6), defensins, lysozyme and collagenase which may directly promote cancer cell intravasation and extravasation." (PMID 26544968, 2015). "Similarly, plasma IL-6 levels were significantly higher in cachectic cancer patients (CC) (p = 0.0119)." (PMID 26732354, 2015). "Because of that, IL-6 has been characterized as a prognostic marker of cancer." (PMID 26418748, 2015). "Furthermore, our work has established for the first time that sunitinib-induced upregulation of PAK1 kinase activity and ensuing NF-κB/IL-6 activation contributed to the accumulation of stem-like cancer cells, RCC progression and sunitinib resistance." (PMID 25675297, 2015). "Furthermore, a study suggested that advanced cancer patients with liver metastasis have higher levels of IL-6." (PMID 26148092, 2015). "Furthermore, the overexpression of HER2 itself regulates EMT by directly activating downstream signaling, such as the PI3K pathway, and the induction of IL-6 release from cancer cells." (PMID 26452030, 2015). "Future experimental studies may validate the potential role up-regulation of Il-6, Cxcl1, Ctgf, and Tgfb2 may have in promoting cancer cell migration, invasion, and cancer-induced bone metabolism." (PMID 27600237, 2015). "IL-6 has been related to many cancer types with a typical pro-tumorigenic effect." (PMID 25797257, 2015). "That is, cancer cells differ in their sensitivities to IL-6 and also GAPDH." (PMID 25785838, 2015). "Therefore, IL-6 appears to be a suitable serological biomarker for malignant tumors of the head and neck." (PMID 25120668, 2014). "This may yield promising results for the future of cancer in terms of adjuvant cancer therapies involving IL-6-induced LNCaP in human CaP cells." (PMID 24520293, 2014). "Patients with tumors at advanced clinical stages (stages III and IV; p < 0.001) and lymph node metastasis (p < 0.001) expressed higher levels of IL-6 and IL-8 double-positive TAMs, suggesting that IL-6 and IL-8 double-positive TAMs are related to cancer progression." (PMID 24885636, 2014). "IL-6, a multifunctional cytokine, has been shown to play a vital role in lots of important biologic activities in a cell- or tissue- specific manner and to be produced by a variety of cells, including cancer cells." (PMID 24664372, 2014). "IL-6 levels were elevated significantly in cancer patients compared with healthy donors." (PMID 25238263, 2014). "Recently, anti-IL-6 moAbs have drawn attention for their potential effects in cancer patients." (PMID 24886605, 2014). "If another TFBS set V$AP1FJ_Q2 is chosen, the well-known c-JUN interacting partner Fos as well as Il6 are captured in the ‘pathways in cancer (KEGG)’ gene set, and Fos exhibits a very strong co-expression pattern with Jun in many of the virus-treated HeLa cell conditions." (PMID 24912499, 2014). "Previous studies confirmed that IL-6 is important in the metastasis of human cancer cells." (PMID 24398980, 2014). "Besides, the tumorigenic effects of IL-17 involve induction of IL-6 production, which in turn activates oncogenic signal transducer and activator of Stat3, which plays essential roles in the pathogenesis of many cancers." (PMID 25489847, 2014).
cancer (continued). "In addition, immunohistochemical examination showed that the cancer cells were positive for G-CSF and IL-6." (PMID 25123545, 2014). "The IL-6/STAT3 pathway plays an important role in human cancers." (PMID 25344679, 2014). "Similarly, another study has shown that IL-6 plays a vital role in promoting cancer stem cells derived from a NSCLC cell line H460." (PMID 26316944, 2014). "Although a role for IL-6 in metastasis has been implicated in some cancer cells, the signaling pathway for IL-6 in cell motility and ICAM-1 expression in human OSCC has not been extensively studied." (PMID 24398980, 2014). "In addition to cell transformation, the expression of IL6, after Src activation, is important for induction and maintenance of cancer stem cells." (PMID 24709904, 2014). "In addition, M-SJDBT significantly inhibited cancer-induced induction of IL-6 and MCP-1 by approximately 50.5% and 90.8%, respectively." (PMID 24963216, 2014). "Since IL-6 could be produced by PC-3 cells and acts in an autocrine or paracrine manner to stimulate cancer growth, we next measured whether the secretion of IL-6 by PC-3 cells is affected by celastrol treatment." (PMID 24664372, 2014). "Most cancers have been found to overexpress IL-6 and have an aberrant IL-6 signaling pathway." (PMID 24664372, 2014). "We thus tested the hypothesis that constitutive AHR signaling may drive IL-6 production also in other human cancer cells." (PMID 24657910, 2014). "Additionally, small molecule compounds for the inhibition of IL-6 or downstream proteins are also developed and being evaluated in preclinical and clinical cancer models." (PMID 24670367, 2014). "Indeed, cancer tissues have lower levels of Let-7 and higher levels of IL6 as compared to normal tissues, and an inverse relationship is also observed in the expression pattern of Let-7 and IL6 in prostate, breast, and hepatocellular tissues." (PMID 24499937, 2014). "The functional analysis using IPA shows that the genes from our pipeline were involved in canonical pathways such as molecular mechanisms of cancer, IL-6 signaling, LPS-stimulated MAPK signaling pathways, iNOS Signaling, EIF2 signaling and mTOR signaling pathways." (PMID 24416147, 2014). "It has been reported that PTHrP protein secreted from cancer cells regulates the expression of the RANKL, IL-6 and IL-8 genes, which have been implicated as factors that enhance osteoclast formation and bone destruction in malignant diseases in osteoblast cells." (PMID 25411851, 2014). "IL-6 has been implicated in maintaining a feedback loop between cancer stem cells and non-stem cancer cells through induction of epithelial-mesenchymal transition, and IL-8 has been implicated in BCSC self-renewal." (PMID 25269750, 2014). "Eight cancers displayed high expression, and 17 cancers showed low expression of IL-6." (PMID 25547486, 2014). "IL-6 is a potent pleyotropic cytokine that may enhance a pro-inflammatory status and promote mechanisms leading to cancer cachexia in the host." (PMID 24886605, 2014). "Moreover, this cancer-promoting activity was due at least in part to the IL-6/STAT-3 signaling pathway." (PMID 25419563, 2014). "IL-6 is a Stat3 activator and is elevated in diverse cancers." (PMID 24453427, 2013). "Moreover, beta-catenin beta-catenin was able to regulate the mRNA stability of several EGF-induced mRNAs, among which the pro-inflammatory cytokine Interleukin 6 (IL6), an acknowledged cancer stem growth factor." (PMID 24260469, 2013). "Furthermore, EGFR blocking, using an αEGFR antibody that neutralizes EGFR by competition with EGF on the external domain of EGFR, also resulted in increases in IL-6 production from cancer cells." (PMID 23592411, 2013). "Solid tumor cells may secrete high levels of IL-6 (as shown here, a process stimulated by stress hormones), which in turn promotes fundamental processes in cancer growth and metastasis including angiogenesis, proliferation, attachment, and invasion." (PMID 23517603, 2013).